ICAM1 (intercellular adhesion molecule 1)
Diseases named in the same sentence as ICAM1 in open-access papers (continued):
Sharing a sentence is not in itself a finding about the gene and the disease.
epilepsy (9 papers, 2012 to 2025). A brain disorder characterized by episodes of abnormally increased neuronal discharge resulting in transient episodes of sensory or motor neurological dysfunction, or psychic dysfunction. "An increase in ICAM-1 expression after TLE seizures has been reported in epilepsy research and is associated with endothelial activation and leukocyte recruitment across the BBB." (PMID 36895367, 2023). "Increased expression of ICAM1 is associated with different cell types in neural disorders including epilepsy." (PMID 22535415, 2012). "Systemic leukocytes infiltrate the brain from the blood stream through VCAM-1 (Vascular Adhesion Molecule 1) and ICAM-1 (Intercellular Adhesion Molecule 1) adhesion molecules, trans-endothelial diapedesis, and blood–brain barrier disruption promoting epilepsy- associated neuroinflammation." (PMID 38166692, 2024). "The results showed that the VCAM-1 and ICAM-1 mRNA levels in the epilepsy group were highest at 24 h after SE, which were significantly higher than those in the control group." (PMID 31572289, 2019). "In this study, ICAM-1 levels were highest in the hippocampus, particularly among the epilepsy cases." (PMID 27737716, 2016). "A set of molecules associated with BBB permeability (MMP-2, MMP-9, S100B), restoration (TIMP-1, TIMP-2, TSP-2), neuroinflammation (CCL-2), and endothelial activation (ICAM-1, P-sel) that are affected in epilepsy and can be measured in blood was selected in this study." (PMID 36766708, 2023). "We propose the Inflammatory Drug-Resistant Epilepsy Index (IDREI), a novel biomarker derived from plasma concentrations of ICAM-1, IL-4, and IL-10 and CSF levels of NfL, for the prediction of DRE." (PMID 40723787, 2025). "Serum levels of MMP-9, MMP-2, TIMP-1, TIMP-2, S100B, CCL-2, ICAM-1, P-selectin, and TSP-2 were examined in a group of 49 patients with epilepsy who were seizure-free for a minimum of seven days and measured by ELISA." (PMID 36499038, 2022). "We found that FK506 not only had direct neuroprotective effects but also inhibited the expression of inflammatory factors VCAM-1, ICAM-1, PKCδ, and TNF-α after seizures, thereby indirectly inhibiting the development of epilepsy." (PMID 31572289, 2019). "Vascular mediators CRP, ICAM-1, and VCAM-1 all showed epilepsy-related differences." (PMID 27737716, 2016). "While some studies have not found significant differences in serum ICAM-1 levels in interictal epilepsy patients compared to controls, others suggest an upregulation of ICAM-1 and other adhesion molecules (e.g., VCAM) in epileptic patients, indicating increased BBB permeability." (PMID 40723787, 2025). "We found increased interictal levels of ICAM-1 in PNES patients without confirmed epilepsy, but cannot exclude that psychiatric comorbidities may have confounded this finding." (PMID 36895367, 2023). "Besides, FK506 also significantly reduced the levels of factors involved in inflammatory response such as vascular cell adhesion molecule-1 (VCAM-1), intercellular adhesion molecule-1 (ICAM-1), tumor necrosis factor-α (TNF-α), and Protein Kinase C δ (PKCδ) that rise after epilepsy." (PMID 31572289, 2019). "Thus, ICAM-1’s involvement in regulating leukocyte trafficking and potentially influencing BBB integrity positions it as a significant contributor to the complex neuroinflammatory cascade observed in patients with epilepsy, potentially impacting disease progression and severity." (PMID 40723787, 2025).
liver disease (9 papers, 2012 to 2025). "ICAM-1 has been suggested to play a role in inflammatory liver diseases by recruiting leukocytes which can injure tissue by releasing various proteases and oxidants." (PMID 23284941, 2012). "Furthermore, both CD40 and ICAM-1 contribute to the inflammatory reaction and fibrosis generation in progressive liver disease." (PMID 24337678, 2014). "Likewise, serum ICAM-1 has shown response to experimental treatment in liver disease." (PMID 33604504, 2021). "Hepatic VCAM-1 was only weakly expressed on human portal ECs but like ICAM-1, VCAM-1 expression was induced or upregulated by inflammatory cytokines and therefore detected at higher levels on vascular and sinusoidal ECs in inflammatory liver diseases." (PMID 31771248, 2019). "In this study, the effectiveness of 1, 25 (OH) 2D3 in attenuating the increasing of NF-κ B, MCP-1, ICAM-1, and TGF-β1 in liver of DM rats suggests that 1,25 (OH) 2D3 might serve as an anti-inflammatory agent for DM liver disease." (PMID 25899686, 2015). "Further, circulating ICAM-1 and VCAM-1 do not exclusively result from liver diseases but are detected in other malignancies as well." (PMID 31771248, 2019).
lymph node metastasis (9 papers, 2015 to 2023). "According to Spearman correlation analysis, the expression of ICAM1 was positively correlated with the expression of MET in the PTC lymph node metastasis group (r = 0.5736, P < 0.0001)." (PMID 37274228, 2023). "Moreover, in patients with lymph node metastases, Kaplan–Meier survival analysis showed that higher ICAM-1 expression had a relatively poor prognosis." (PMID 35487888, 2022). "Interestingly, lymph node metastases seem to have higher ICAM-1 expression than distant metastases but this difference was not statistically significant (p = 0.068)." (PMID 29245925, 2017). "It is still unclear why there may be an association between prognosis and ICAM-1 expression on distant metastases but not lymph node metastases." (PMID 29245925, 2017). "For validation at the experimental level, the expression of PTGS2, MET, and ICAM1 was analyzed via immunohistochemical staining of pathological sections from the lymph node metastasis and non-metastasis groups." (PMID 37274228, 2023). "MET and ICAM1 had strong staining in the lymph node metastasis group and weak staining in the lymph node non-metastasis group." (PMID 37274228, 2023). "ICAM-1 expression in distant metastases demonstrated a trend towards a higher level than in lymph node metastases which was not significant statistically (p = 0.09)." (PMID 29245925, 2017). "It was found that reduced/absent MHC I expression correlated significantly with lymph node metastases as did a lack of ICAM-1 expression." (PMID 27189371, 2016). "However, IHC showed that the expression of MET and ICAM1 significantly differed between the lymph node metastasis and non-metastasis groups." (PMID 37274228, 2023). "Furthermore, we found that ICAM-1 expression was higher in patients with lymph node metastases than in patients with non-lymph node metastases using the TCGA database." (PMID 35487888, 2022). "According to the IHC staining results, the lymph node metastasis group had a higher expression of MET and ICAM1 than the lymph node non-metastasis group." (PMID 37274228, 2023).
non-small cell lung carcinoma (9 papers, 1998 to 2024). A group of at least three distinct histological types of lung cancer, including non-small cell squamous cell carcinoma, adenocarcinoma, and large cell carcinoma. "Patients with non-small-cell lung cancer have been shown to have higher serum levels of sICAM-1 (soluble ICAM-1) and increased ICAM-1 expression." (PMID 30657059, 2019).
oral cancer (9 papers, 2013 to 2023). "We analyzed contributions of different haplotype combinations of 4 ICAM-1 SNPs (rs3093030, rs5491, rs281432, and rs5498) to the risk of oral cancer and eventually found that the TAGG or TACG haplotype showed a high risk for OSCC." (PMID 24069166, 2013). "The current study investigated relationships of SNPs (rs3093030, rs5498, rs5491, and rs281432) of the ICAM-1 gene with the risk of oral cancer." (PMID 24069166, 2013). "In contrast to rs5498, we also found that oral-cancer patients with 1 T allele of ICAM-1 rs5491 or 1 G allele of ICAM-1 rs281432 showed a significant lower risk for being at an advanced clinical stage." (PMID 24069166, 2013). "Adjusted odds ratio (AOR) and 95% confidence interval (CI) of oral cancer associated with ICAM-1 genotypic frequencies and smokers among 549 betel nut consumers." (PMID 24069166, 2013). "Adjusted odds ratio (AOR) and 95% confidence interval (CI) of oral cancer associated with ICAM-1 genotypic frequencies and betel nut chewing among 727 smokers." (PMID 24069166, 2013). "The synergistic effects of environmental factors (betel-nut and smoking) and 4 ICAM-1 gene SNPs (rs3093030, rs5491, rs281432, and rs5498) on the risk of oral cancer are well demonstrated." (PMID 24069166, 2013). "Patients with oral cancer who carry at least 1 T allele of ICAM-1 rs5491 or 1 G allele of ICAM-1 rs281432 have a lower risk of developing an advanced clinical stage compared to patients carrying A/A or C/C homozygotes." (PMID 24069166, 2013). "In this study, we first investigated whether polymorphisms within the ICAM-1 gene likely played a significant role in the susceptibility to and development of oral cancer." (PMID 24069166, 2013). "In our study, only ICAM-1 rs5498 SNPs alone contributed to oral-cancer susceptibility." (PMID 24069166, 2013). "Gene-environment interactions of ICAM-1 polymorphisms, smoking, and betel-nut chewing might alter oral-cancer susceptibility." (PMID 24069166, 2013). "Finally, patients with oral cancer who had at least 1 T allele of ICAM-1 rs5491 or 1 G allele of rs281432 were at lower risk of developing an advanced clinical stage (III/IV) (p<0.05), compared to those patients with AA or CC homozygotes." (PMID 24069166, 2013). "In conclusion, our results suggest that ICAM-1 polymorphic rs5498 might be correlated with susceptibility to oral cancer, and combined effects of ICAM-1 gene polymorphisms with environmental carcinogens significantly increase the risk of developing oral cancer." (PMID 24069166, 2013). "CCL2/CCR2 and intercellular adhesion molecule-1 (ICAM-1) are other important pathways that stimulate the recruitment of TAMs into oral cancers." (PMID 37221555, 2023). "ICAM-1 is a transmembrane glycoprotein in the immunoglobulin superfamily, which participates in oral cancer progression and induces macrophage/SCC-cell adhesion." (PMID 25907256, 2015). "We found that the ICAM-1 rs5498 polymorphism and the TAGG or TACG haplotype of 4 ICAM-1 SNPs (rs3093030, rs5491, rs281432, and rs5498) combined were associated with oral-cancer susceptibility." (PMID 24069166, 2013). "Recently, it was shown that ICAM-1 possibly contributes to tumorigenesis and metastasis including oral cancer." (PMID 24069166, 2013). "Previous research has shown that EP1 upregulates ICAM-1 levels in oral cancer cells." (PMID 26648273, 2015). "Among oral cancers, ICAM-1 is expressed predominantly at the invasive front of tongue squamous cell carcinoma (SCC) and positively correlated with invasion, lymph node metastasis and increased density of circulating cancer cells in the blood and lymphatic vessels." (PMID 26231039, 2015). "Alleles with the highest distribution frequency for the rs3093030, rs5491, rs281432, and rs5498 genes of ICAM-1 in both of our recruited oral-cancer patients and healthy controls were respectively homozygous for C/C, homozygous for A/A, homozygous for C/C, and homozygous for A/A." (PMID 24069166, 2013).
oral cancer (continued). "Clinical status and ICAM-1 genotypic frequencies in 595 oral cancer patients." (PMID 24069166, 2013). "Distribution frequency of ICAM-1 haplotype in controls and oral cancer patients." (PMID 24069166, 2013). "Among 549 betel-nut chewers, ICAM-1 polymorphisms carriers who smoked had a 9.93–14.27-fold greater risk of having oral cancer compared to those who carried the WT but did not smoke." (PMID 24069166, 2013). "Four single-nucleotide polymorphisms (SNPs) of the ICAM-1 gene from 595 patients with oral cancer and 561 non-cancer controls were analyzed by a real-time PCR." (PMID 24069166, 2013). "Among 727 smokers, ICAM-1 polymorphisms carriers with the betel-nut chewing habit had a 27.49–36.23-fold greater risk of having oral cancer compared to ICAM-1 wild-type (WT) carriers without the betel-nut chewing habit." (PMID 24069166, 2013). "Distribution frequency of ICAM-1 genotypes in 561 healthy controls and 595 oral cancer patients." (PMID 24069166, 2013). "Moreover, people who were either polymorphic for ICAM-1 in 4 loci (rs3093030, rs5491, rs281432, and rs5498) or who smoked were at a 4.17∼8.06-fold risk (p<0.05) of developing oral cancer, compared to people with the WT gene who did not smoke." (PMID 24069166, 2013). "In oral cancer, prostaglandin E2 (PGE2) induced cell motility through ICAM-1 up-regulation." (PMID 23803661, 2013). "In oral cancer, COX-2 is of importance for maintaining a chronic inflammatory state, influencing different processes, such as cell migration by upregulating the expression of intercellular adhesion molecule-1 (ICAM-1) via PGE2, and lymphoangiogenesis by regulating VEGF production." (PMID 35047997, 2021).
periodontal disease (9 papers, 2014 to 2025). "Butyrate is necessary in immune processes associated with periodontal disease by reducing the expression of the adhesion protein intercellular adhesion molecule-1 (ICAM-1) and the transmigration of immune cells, as well as reducing mediator production and neutrophil phagocytosis." (PMID 39228377, 2024). "In summary, we have identified ICAM1 as a cell surface marker to distinguish inflammatory fibroblasts that exert a protective immune function during early periodontal disease process." (PMID 39650645, 2024). "ICAM1+ fibroblasts have been shown to directly interact and downregulate T cell responses in vitro, and similar mechanisms may affect periodontal disease progression, which may be investigated in future studies." (PMID 39650645, 2024). "It is plausible that the ICAM1+ inflammatory fibroblasts shift their secretome profile to accommodate a transition from the innate to adaptive immune response toward the later stages of periodontal disease." (PMID 39650645, 2024). "Future research exploring the effects of V. parvula OMVs in vivo and the subsequent relationship between ICAM-1+ neutrophils and NET formation would be a point of focus in revealing the mechanisms of periodontal diseases and discovering new therapeutic strategies." (PMID 40568695, 2025). "AGEs increase IL-6 and intercellular adhesion molecule-1 (ICAM-1) expression via the RAGE, MAPK, and nuclear factor-κB (NF-κB) pathways in human gingival fibroblasts and exacerbate the progression of the pathogenesis of periodontal diseases." (PMID 34539410, 2021).
proliferative diabetic retinopathy (9 papers, 2011 to 2024). Advanced retinopathy due to diabetes mellitus characterized by the formation of new vessels in the retina. "Association of VEGF and ICAM-1 with severity of retinopathy (non proliferative and proliferative diabetic retinopathy)." (PMID 23922493, 2013). "In addition to its association with sICAM1 levels, the ICAM1 SNP rs5498 has been shown to associate with a plethora of diseases in Asians including diabetic microvascular complications, proliferative diabetic retinopathy, oral carcinogenesis, migraine, and coronary atherosclerosis." (PMID 28095483, 2017). "Previous studies have indicated that ICAM-1 expression is increased in posterior uveitis, proliferative vitreoretinopathy, proliferative diabetic retinopathy and AMD." (PMID 31212975, 2019). "The author mentioned that the proliferative diabetic retinopathy mediated through increased NF-κB, VEGF and ICAM-1 in the retina." (PMID 35335970, 2022). "In particular, increased expression of cell adhesion molecules such as VCAM1, ICAM1, and ICAM2 is a feature of proliferative diabetic retinopathy (PDR), where they increase recruitment of leukocytes to the endothelium and disrupt blood flow, a process termed leukostasis." (PMID 32811565, 2020). "Comparisons of migration inhibitory factor (MIF), vascular endothelial growth factor (VEGF) and soluble intercellular adhesion molecule-1 (sICAM-1) in vitreous samples from patients with proliferative diabetic retinopathy (PDR) and nondiabetic patients with rhegmatogenous retinal detachment (RD)." (PMID 31866994, 2019).
acute coronary syndrome (8 papers, 2013 to 2025). Signs and symptoms related to acute ischemia of the myocardium secondary to coronary artery disease. "Enzymatic studies conducted on IMAs removed from patients with acute coronary syndrome or chronic stable angina have shown low expression of inducible nitric oxide synthase (iNOS) and intercellular adhesion molecule-1 (ICAM-1)." (PMID 41009616, 2025). "Another study reported significantly increased (p < 0.05) serum ICAM-1 levels in acute coronary syndrome patients, and serum ICAM-1 levels were higher in patients with PSCS." (PMID 29403392, 2018). "Serum ICAM-1 levels are linked to macrovascular disease, and serum VCAM-1 concentrations have been correlated with the occurrence of acute coronary syndrome." (PMID 25955252, 2015).
brain edema (8 papers, 2017 to 2025). Increased intracellular or extracellular fluid in brain tissue. "For example, administration of fenofibrate after TBI led to improved neurological scores, reduced cerebral edema, lesion volume and ICAM-1 expression in a rat model." (PMID 28603485, 2017). "Nevertheless, the mechanisms through which CAPE ameliorates cerebral edema from a peripheral perspective may involve more than the regulation of VCAM-1 and ICAM-1." (PMID 41567629, 2025).
brain injury (8 papers, 2014 to 2024). Acute and chronic (see also brain INJURIES, CHRONIC) injuries to the brain, including the cerebral hemispheres, CEREBELLUM, and brain STEM. "A strong correlation exists between traumatic brain injury-mediated inflammation and impairment in functional outcomes following brain trauma and concentration of ICAM-1." (PMID 38473707, 2024). "This indicates that ICAM-1 has significant role in transmigration of leukocytes following brain injury." (PMID 34135004, 2021). "Gut barrier dysfunction and enhanced translation of NF-κB, TNF-a, IL-1b, IL-6, and ICAM-1 were observed in Nrf2−/− mice after traumatic brain injury." (PMID 27009867, 2016). "Upregulation of ICAM-1 in cerebral microvessels has been described in several brain pathologies, including brain trauma." (PMID 25972624, 2015). "Although a strong correlation exists between TBI-mediated inflammation and impairment in functional outcome following brain trauma, the role of ICAM-1 in impairing functional outcome by inducing neuroinflammation and neurodegeneration after TBI remains inconclusive." (PMID 34135004, 2021). "Similar effects have been reported in studies of ischemic brain injury, whereby reductions in immune cell trafficking accompanied CB2R agonist-induced decreases in ICAM-1 expression and BBB damage." (PMID 25416141, 2014). "In our study we proposed that vitamin C could attenuate the vascular endothelial inflammatory response after traumatic brain injury in rats with the reduction of ICAM-1 level and it was never mentioned before." (PMID 25013810, 2014).
cardiac hypertrophy (8 papers, 2014 to 2025). "Only few cell adhesion molecules, such as β-1D integrin, neural cell adhesion molecule (NCAM), and intercellular adhesion molecule-1 (ICAM-1) are involved in cardiac hypertrophy." (PMID 31091274, 2019). "Another research by Al-Asoom et al22 showed that 800 mg/kg/day N. sativa suspension for 8 weeks did not cause significant change in serum ICAM-1 level in rats with physiological cardiac hypertrophy compared with the control arm." (PMID 40365513, 2025). "The 2 weeks AngII infusion induced cardiac hypertrophy and aortic damage that persisted beyond AngII interruption and despite blood pressure normalization, with a sustained vascular expression of ICAM1, infiltration by CD45+ cells, and cell proliferation associated with systemic oxidative stress." (PMID 35360022, 2022).